FAM89A (family with sequence similarity 89 member A)
Synonyms: C1orf153; MGC15887
Tractability: No criterion of Open Targets' tractability assessment is met for any kind of drug.
Gene: Protein-coding gene on chromosome 1 (231,018,958 to 231,040,254, reverse strand). Ensembl gene ENSG00000182118.
Subcellular location (Human Protein Atlas): Golgi apparatus; Vesicles; Nucleoplasm
Genetic constraint (gnomAD): Loss-of-function variants: 11 observed, 6.22 expected, observed/expected ratio (o/e) 1.77, 90% interval 1.02 to 1.96. That is too few expected variants to judge how well the gene tolerates losing a copy. Missense variants: 276 observed, 198.46 expected, observed/expected ratio (o/e) 1.39, 90% interval 1.26 to 1.54. Synonymous variants: 157 observed, 101.12 expected, observed/expected ratio (o/e) 1.55, 90% interval 1.36 to 1.77.
Homologues: Orthologues: chimpanzee FAM89A (99% identical), macaque FAM89A (97% identical), dog FAM89A (91% identical), pig FAM89A (84% identical), guinea pig FAM89A (80% identical), mouse Fam89a (80% identical), rat Fam89a (79% identical), tropical clawed frog fam89a (66% identical), zebrafish fam89a (52% identical), Drosophila melanogaster CG31038 (34% identical), Drosophila melanogaster lmgB (32% identical). Paralogues in human: FAM89B (44% identical), TRANK1 (33% identical).
Diseases named in the same sentence as FAM89A in open-access papers:
FAM89A is named in the same sentence as 8 diseases in open-access papers, as found by Europe PMC text mining. Sharing a sentence is not in itself a finding about the gene and the disease. The quoted sentences say what the papers report.
viral infections (5 papers, 2018 to 2023). "Specifically, the rs4543780, the intronic variant of FAM89A gene, was associated with total antibodies level and was annotated as a potential regulatory variant affecting gene expression of FAM89A, a biomarker differentiating bacterial from viral infections in febrile children." (PMID 36451823, 2022). "In this study, we investigated whether whole-blood RNA expression of the genes FAM89A and IFI44L from children with FN could be used as a diagnostic tool to discriminate bacterial from viral infections." (PMID 37371198, 2023). "Though the function of FAM89A gene is not well studied, researches indicated that FAM89A gene, together with IFI44L gene, was capable of differentiating between bacterial and viral infections with high sensibility and specificity, suggesting that FAM89A gene might be involved in immune response." (PMID 36451823, 2022).
glioma (2 papers, 2019 to 2025). A benign or malignant brain and spinal cord tumor that arises from glial cells (astrocytes, oligodendrocytes, ependymal cells). "Abnormal methylation of FAM89A has also been reported in glioma, and the gene shows prenatal relevance." (PMID 41301891, 2025).
Sepsis (2 papers, 2023 to 2024). Sepsis is defined as life-threatening organ dysfunction caused by a dysregulated host response to infection. "The identified FAM89A, FFAR3, G0S2, and FGF13 genes may help elucidate the molecular mechanisms underlying sepsis and drive the introduction of new biomarkers to advance diagnosis and treatment." (PMID 38050254, 2023).
Immunodeficiency (1 paper, 2022). Failure of the immune system to protect the body adequately from infection, due to the absence or insufficiency of some component process or substance. "The Family with Sequence Similarity 89 Member A (FAM89A) and the Interferon Induced Protein 44 Like (IFI44L) are both protein coding genes that have been linked to a rare mild immunodeficiency (immunodeficiency 38 with basal ganglia calcification)." (PMID 35186993, 2022).
bacterial infection (5 papers, 2018 to 2025). "FAM89A expression is upregulated during bacterial infection and helps distinguish bacterial from viral causes." (PMID 41301891, 2025). "IFI4L was noted to be increased in antiviral responses mediated by interferons, while FAM89A was increased in bacterial infections and septic shock thus forming a reciprocal relationship of upregulation between both genes in viral and bacterial infections." (PMID 35186993, 2022). "Here, we have shown that a RT-qPCR assay for a 2-transcript host expression signature (FAM89A and IFI44L genes) inferred from microarray data is able to efficiently separate viral from bacterial infections." (PMID 31409879, 2019).
FAM89A also shares sentences with these, for which no sentence is quoted: COVID-19 (1 paper); influenza infection (1); tumor (1).